MGMT (O-6-methylguanine-DNA methyltransferase)
Diseases named in the same sentence as MGMT in open-access papers (continued):
Sharing a sentence is not in itself a finding about the gene and the disease.
glioblastoma (continued). "More recently, the results of the EORTC-NCIC trial have established a predictive value for MGMT methylation status for the benefit from TMZ treatment achieved by patients with glioblastoma." (PMID 25955568, 2015). "O6-methylguanine-DNA-methyltransferase (MGMT) has emerged as a relevant predictor of therapeutic response and good prognosis in patients with glioblastoma (GBM)." (PMID 26347581, 2015). "Gene therapy has been used to express the O6BG-resistant MGMT mutant P140 K in haematopoietic cells of glioblastoma patients, which has allowed them to receive more intensive chemotherapy." (PMID 26702034, 2015). "Two molecular biomarkers of significant interest for glioblastoma involve isocitrate dehydrogenase (IDH) mutations and O6-methylguanine-DNA methyltransferase (MGMT) promoter methylation." (PMID 26503470, 2015). "O6-methylguanine-methyltransferase (MGMT) promoter methylation status has prognostic and, in the subpopulation of elderly patients, predictive value in newly diagnosed glioblastoma." (PMID 26295302, 2015). "In fact, MGMT methylation is now routinely used for selection of glioblastoma patients for temozolomide treatment." (PMID 26506390, 2015). "Hypermethylation of the MGMT gene has been shown to be associated with improved outcome in glioblastoma (GBM) and may be a predictive marker of sensitivity to chemotherapy with alkylating agents and to radiation therapy in GBM." (PMID 26490252, 2015). "Our data therefore, suggest a potential therapeutic utility of BMP7, a neuroprotective agent in cerebral hypoxia/ischemia, combined with TMZ, for treating newly diagnosed glioblastoma or recurrent diseases exhibiting unmethylated MGMT." (PMID 26546412, 2015). "Another study of 105 patients with glioblastoma showed that extent of resection, MGMT promoter methylation status and YKL-40 expression by immunohistochemistry were the most important prognostic factors in newly diagnosed glioblastomas." (PMID 24809021, 2014). "miR-603 transfection enhanced the temozolomide (TMZ) sensitivity of MGMT-expressing glioblastoma cell lines." (PMID 24994119, 2014). "Previous reports suggest miR-221/mir-222, miR-767-3p, and miR-648 as potential MGMT regulating miRNAs in glioblastoma." (PMID 24994119, 2014). "Consistently reported prognostic factors for glioblastoma (GBM) are age, extent of surgery, performance status, IDH1 mutational status, and MGMT promoter methylation status." (PMID 25233099, 2014). "More recently, two independent phase III studies showed that the MGMT promoter methylation status is of predictive value in the subpopulation of elderly glioblastoma patients." (PMID 24359605, 2014). "This study was performed to define the prognostic and predictive value of MGMT promoter methylation in Chinese glioblastoma patients." (PMID 25211033, 2014). "In summary, the meta-analysis highlights the therapeutic implications of MGMT promoter status for a better treatment choice of elderly glioblastoma patients." (PMID 24454798, 2014). "Given the essential role of APE1, NBN, PTEN, PMS2 and MGMT in adult tumours we explored if these genes also influence outcomes in paediatric high grade gliomas/glioblastomas." (PMID 25026297, 2014). "Promoter methylation of the O6-methylguanine-DNA-methyltransferase (MGMT) gene has been considered a prognostic marker and has become more important in the treatment of glioblastoma." (PMID 25211033, 2014). "In the present study, we investigated the mechanism of HOXA10 regarding its role in temozolomide resistance using glioblastoma cell lines and tested the therapeutic implication of temozolomide resistance in conjunction with MGMT status." (PMID 25061500, 2014). "A notable example is the association between the silencing of the O6-methylguanine-DNA methyltransferase (MGMT) gene and the improved response to temozolomide and radiation in patients with glioblastoma." (PMID 25486910, 2014).
glioblastoma (continued). "The epigenetic mark of O6-methylguanine–DNA methyltransferase (MGMT) promoter methylation is also taken under consideration for glioblastoma patients, as it was proven to correlate with survival, following temolozomide treatment." (PMID 25298751, 2014). "Salient to this review, testing for promoter CpG island methylation of DNA repair gene O6-methylguanine-DNA methyltransferase, MGMT, guides the clinical management of glioblastoma." (PMID 24375389, 2014). "To identify miRNAs that suppressed MGMT expression, we individually transfected 885 known miRNAs (Human miScript miRNA mimic 96 set, Qiagen) into T98G, a glioblastoma cell line that showed high expression of MGMT." (PMID 24994119, 2014). "Other studies have also shown MGMT methylation to be prognostic in glioblastoma patients given chemoradiotherapy." (PMID 24952577, 2014). "Two recent and independent phase III therapy trials confirmed a prognostic and predictive value of the MGMT promoter methylation status in elderly glioblastoma patients." (PMID 24359605, 2014). "Glioblastoma patients with more than 29% MGMT promoter methylation showed a longer progression-free and overall survival when treated with radiotherapy and Temozolomide." (PMID 25229548, 2014). "Testing of the MGMT promoter methylation status in glioblastoma is relevant for clinical decision making and research applications." (PMID 24359605, 2014). "More importantly, the study encouraged routine testing of MGMT promoter status especially in elderly glioblastoma patients by indicating a direct linkage between biomarker test and individual treatment decision." (PMID 24454798, 2014). "Two glioblastoma cell lines with different MGMT statuses were used to test the augmented anticancer effect of temozolomide with HOXA10 inhibition." (PMID 25061500, 2014). "The clinical implication of O6-methylguanine-DNA methyltransferase (MGMT) promoter status is ill-defined in elderly glioblastoma patients." (PMID 24454798, 2014). "Promoter region hypermethylation-induced MGMT gene silencing has been reported in glioblastoma multiforme, head, and neck squamous cell carcinomas in general, and also specifically in oral cavity cancer." (PMID 24991542, 2014). "Similar findings have been previously observed for MGMT methylation vs. expression as predictor for response to alkylating agents in glioblastoma." (PMID 25222296, 2014). "In a collection of 74 clinical glioblastoma specimens, both miR-603 and miR-181d levels inversely correlated with MGMT expression." (PMID 24994119, 2014). "Our article summarizes clinical indications, practical instructions and open issues for MGMT promoter methylation testing in glioblastoma using pyrosequencing." (PMID 24359605, 2014). "This is complicated by the fact that MGMT methylation status can change between the first surgery for newly diagnosed glioblastomas, and the second surgery for a recurring tumor." (PMID 24937153, 2014). "MGMT promoter methylation testing by means of pyrosequencing fulfills the criteria of high clinical utility for predictive purposes in elderly glioblastoma and for prognostic purposes in all adult glioblastoma patients." (PMID 24359605, 2014). "We then hybridized this dataset to identify the miRNAs whose expression inversely correlated with the expression of MGMT in MGMT promoter unmethylated glioblastomas." (PMID 24994119, 2014). "These primary glioblastoma cells were characterized for their MGMT promoter methylation status and MGMT protein expression." (PMID 24495907, 2014). "It was also clear that there is a correlation between IDH1/2 mutation and MGMT methylation and also IDH1/2 mutation and PTEN status which is present in both grade III tumours and primary glioblastomas." (PMID 24952577, 2014). "O6-methylguanine-DNA methyltransferase (MGMT) promoter methylation is reported to be a prognostic and predictive factor of alkylating chemotherapy for glioblastoma patients." (PMID 25175833, 2014).
glioblastoma (continued). "High MGMT expressing, patient-derived glioblastoma xenografts (GBM12TMZ and 43TMZ) that were serially passaged in murine flank were injected with miR-603 or non-targeting miRNA (4 tumors per condition)." (PMID 24994119, 2014). "Of particular importance in glioblastoma is the DNA repair protein O6-methlyguanine methyl transferase – MGMT – (10q26)." (PMID 24716189, 2014). "Based on the results of two recent phase III clinical trials and the confirmed assay reliability, MGMT pyrosequencing fulfills the criteria for high clinical utility and is recommended for therapy planning in elderly glioblastoma patients." (PMID 24359605, 2014). "In line with this assumption, the MGMT promoter methylation status influences the outcome of patients with glioblastoma treated with temozolomide." (PMID 24359605, 2014). "In other tumours, such as glioblastoma multiforme, metronomic schedule of temozolomide has been reported to overcome O-6-methylguanine-DNA methyltransferase (MGMT)-related resistance." (PMID 25228919, 2014). "So far, the MGMT status is the only established prognostic and predictive factor in the therapy of glioblastoma with chemotherapeutics." (PMID 23704990, 2013). "Within glioblastoma specimens, PDGFRA amplification alone was linked to oligodendroglial, small cell and sarcomatous tumour cell morphologies, and rare MGMT promoter methylation." (PMID 23990986, 2013). "MGMT status is recognized as a strong predictor for the survival of newly diagnosed glioblastoma patients treated with RT and TMZ." (PMID 24265731, 2013). "Methylation of the MGMT promoter occurs in approximately 45% of newly diagnosed glioblastoma patients and is prognostic for response to TMZ treatment." (PMID 24287492, 2013). "We therefore investigated promoter methylation of ABCB1 and ABCG2 in 64 glioblastoma patients using the pyrosequencing technology, which allows unequivocal quantification of the methylation status, and used MGMT promoter methylation as positive control." (PMID 24380367, 2013). "The main enzyme responsible for glioblastoma multiform (GBM) resistance to TMZ is O6-MG-DNA methyltransferase (MGMT), which takes off the methyl adducts from the DNA." (PMID 23445763, 2013). "MGMT promoter methylation is the only potentially predictive marker, especially for alkylating agent chemotherapy in glioblastoma." (PMID 24160898, 2013). "A predictive value of MGMT promoter methylation status for response to temozolomide-based chemotherapy in elderly glioblastoma patients is supported by two independent prospective randomized clinical trials." (PMID 23618424, 2013). "ZEB1, N-cadherin, ROBO1, MGMT and Engrailed1 are frequently expressed in glioblastoma, confirming our experimental findings." (PMID 23818228, 2013). "Several studies predict MGMT promoter methylation as an important prognostic factor for clinical outcome of glioblastoma patients treated with temozolomide." (PMID 24380367, 2013). "First, the sensitivity of glioblastoma cells to TMZ is inhibited by the expression of O-6-methylguanine-DNA methyltransferase (MGMT)." (PMID 24265816, 2013). "The DNA methylation of MGMT has been found to be a more reliable predictor of outcomes in glioblastoma patients." (PMID 24345474, 2013). "In summary, our study represents a combined investigation of promoter methylation and gene polymorphisms of the pivotal drug resistance genes MGMT, ABCB1 and ABCG2 in glioblastoma multiforme." (PMID 24380367, 2013). "A well-studied example of a hypermethylated gene in GBM with important consequences for clinical management is MGMT, a DNA repair enzyme that is methylated in 68% of glioblastomas." (PMID 22771539, 2013). "In glioblastoma, a high prognostic clinical performance of MGMT promoter methylation status has been robustly confirmed." (PMID 23618424, 2013).
glioblastoma (continued). "In this manuscript, we provide evidence that miR-221 and miR-222 regulate MGMT expression levels in glioblastoma, increasing the response to TMZ, but due to their oncogenic potential, affect overall patient survival negatively." (PMID 24147153, 2013). "The high prognostic value of MGMT methylation in glioblastoma has been confirmed by many studies including prospective trial data." (PMID 23618424, 2013). "Using chromatin immunoprecipitation, we confirmed that c-MYB binds to the MGMT promoter in glioblastoma cells." (PMID 23818228, 2013). "The only candidate biomarkers, for which published literature indicates a high predictive clinical performance is MGMT testing in glioblastomas of the elderly and 1p19q status in anaplastic oligodendroglial tumors." (PMID 23618424, 2013). "In other previous studies, the correlation between immunohistochemically determined MGMT expression and the survival of glioblastoma patients treated with TMZ is controversial." (PMID 24265731, 2013). "A recent meta-analysis of glioblastoma studies concluded that patients with a hypermethylated MGMT promoter status had significantly greater overall survival and progression-free survival than those without a methylated MGMT promoter." (PMID 24152442, 2013). "In glioblastoma specimens gene methylation was observed as follows: MGMT in 51.3%, GATA6 in 68.4%, CD81 in 46.1%, DR4 in 41.3% and CASP8 in 56.8% of tumors." (PMID 22672670, 2012). "More recently, reports of the EORTC and NCIC trial 26981-22981/CE.3 have established the predictive value of low MGMT methylation for benefit from TMZ treatment in patients with glioblastoma." (PMID 22837675, 2012). "Promoter methylation of the repair gene O6-methylguanine-DNA methyltransferase (MGMT) is a predictive factor for benefit from alkylating agent therapy in glioblastoma patients." (PMID 22810491, 2012). "In this study pyrosequencing came across as a slightly better method than qMSP when looking at the prognostic value of MGMT promoter methylation status in primary glioblastomas." (PMID 22390413, 2012). "Taken together, our findings corroborate earlier conclusions that MGMT promoter methylation is of prognostic value for primary glioblastoma patients, and this status is of interest for the patients, their relatives, and treating physicians." (PMID 22390413, 2012). "It remains to be seen if in this CIMP-negative patient subpopulation the MGMT status is predictive for benefit from alkylating agent therapy like in glioblastoma or has a prognostic value." (PMID 22810491, 2012). "High methylation frequency of tested genes shows heterogeneity of glioblastoma epigenome and the importance of MGMT, GATA6 and CASP8 genes methylation in glioblastoma patient outcome." (PMID 22672670, 2012). "Gene silencing of O6-methylguanine–DNA methyltransferase (MGMT) by promoter methylation improves the outcome of glioblastoma patients after combined therapy of alkylating chemotherapeutic agents and radiation." (PMID 23110891, 2012). "In 2005, a seminal paper showed that glioblastoma patients aged 18 to 70, whose tumors have a methylated MGMT promoter have a better prognosis than patients with tumors carrying an unmethylated MGMT promoter." (PMID 23083460, 2012). "The MGMT promoter methylation status is the strongest prognostic factor for outcome in patients with newly diagnosed glioblastoma and is a powerful predictor of response to alkylating chemotherapy." (PMID 22908046, 2012). "In agreement with numerous studies where the methylation of MGMT was detected in approximately 40%-48% of primary glioblastomas, our study showed a methylation frequency of 51%." (PMID 22672670, 2012). "The MGMT promoter is typically reported methylated in 30-60% of glioblastomas and in 30-90% of low-grade gliomas." (PMID 22390413, 2012). "The activity of temozolomide in glioblastoma patients relies on gene silencing of the MGMT (O6-methylguanine–DNA methyltransferase) DNA repair gene, though." (PMID 23110891, 2012).
glioblastoma (continued). "The rationale behind the study was that glioblastoma patients with MGMT gene silencing benefit from chemotherapy with the alkylating agent temozolomide in combination with radiation therapy." (PMID 23110891, 2012). "Methylation of the O6-methylguanine-DNA methyltransferase (MGMT) gene promoter is a favorable prognostic factor in glioblastoma patients." (PMID 22390413, 2012). "The analysis of the MGMT gene in glioblastoma using HM-450K methylation data has shown a strong CpG location-dependent effect on patient outcome." (PMID 22810491, 2012). "In line with this assumption an influence of the MGMT promoter methylation status on the outcome of patients with glioblastoma treated with the alkylans temozolomide has repeatedly been observed." (PMID 23083460, 2012). "Worse still, many glioblastomas are found to be resistant to chemo- or radiotherapy due to DNA repair by the protein O6-methylguanine-methyltransferase (MGMT) and impaired apoptotic pathways." (PMID 23050142, 2012). "The methylation status of the O6-methylguanine-DNA methyltransferase (MGMT) gene is an important predictive biomarker for benefit from alkylating agent therapy in glioblastoma." (PMID 22810491, 2012). "Six glioblastomas (24%), 3 diffuse astrocytomas (30%), and 1 anaplastic astrocytoma (17%) showed MGMT promoter hypermethylation." (PMID 22389839, 2012). "Our results showed that the T98G and U-87 glioblastoma cell lines were both methylated at the MGMT gene promoter, while the primary human fibroblasts IMR-90 had unmodified MGMT alleles." (PMID 21752281, 2011). "Similar results in terms of no statistical significance were obtained when considering the status of MGMT protein expression in the same subgroup of glioblastomas (P = 0.2309)." (PMID 21752281, 2011). "O6-methylguanine DNA-methyltransferase (MGMT) promoter methylation has been identified as a potential prognostic marker for glioblastoma patients." (PMID 21249131, 2011). "The promoter of the MGMT gene has been found to be hypermethylated at a high frequency in many types of cancers, including colorectal cancer and glioblastoma." (PMID 21108794, 2010). "Patients with glioblastoma containing a methylated MGMT promoter showed a major benefit from temozolomide." (PMID 20167086, 2010). "In glioblastoma, promoter methylation of the counteracting DNA repair enzyme O6-methylguanine-DNA-methyltransferase (MGMT) correlates with survival of patients exposed to TMZ in combination with radiotherapy." (PMID 20736948, 2010). "Around half of all glioblastoma patients harbour an unmethylated MGMT promoter, and these seem to respond poorly to temozolomide chemotherapy." (PMID 20515495, 2010). "As such a study would be very difficult to perform in humans, we attempted to measure the effects of standard and dose-intense temozolomide schedules on human glioblastoma MGMT activity using an orthotopic xenograft model." (PMID 20628383, 2010). "Using the clinically relevant schedules from the RTOG 0525 trial, we determined that a dose-intense temozolomide schedule is more effective than a standard dose schedule at depleting MGMT activity in human glioblastoma using an orthotopic xenograft model." (PMID 20628383, 2010). "Human glioblastoma cells (GBM43) with an unmethylated MGMT promoter were implanted intracranially in immunodeficient rodents." (PMID 20628383, 2010). "Less than 40% of patients with newly diagnosed glioblastoma have inhibited expression of MGMT because of hypermethylation of the MGMT promoter, and 2-year survival in this group when treated with temozolomide approached 50% on the EORTC 22981/26981 study." (PMID 20628383, 2010). "Following incomplete surgical resection, the patient was diagnosed with glioblastoma multiforme expressing hypermethylation of the MGMT gene promoter." (PMID 20412570, 2010). "O6-methylguanine-DNA methyltransferase (MGMT) expression in glioblastoma correlates with temozolomide resistance." (PMID 20628383, 2010).